LINC00896 (long independently transcribed non-coding RNA 896)
Synonyms: FLJ32575
Gene: Long non-coding RNA gene on chromosome 22 (20,206,340 to 20,235,981, forward strand). Ensembl gene ENSG00000236499.
Diseases named in the same sentence as LINC00896 in open-access papers:
LINC00896 is named in the same sentence as 3 diseases in open-access papers, as found by Europe PMC text mining. Sharing a sentence is not in itself a finding about the gene and the disease. The quoted sentences say what the papers report.
cancer (1 paper, 2017). A tumor composed of atypical neoplastic, often pleomorphic cells that invade other tissues. "In their results, 160 lncRNAs were found to be dysregulated in cancer, of which seven were found in our 658 lncRNA list (LOC645949, LINC00896, FAM99B, LINC00167, LINC01056, SND1-IT1, NCBP2-AS2)." (PMID 28415559, 2017).
tumor (1 paper, 2024). "This suggests that the overexpression of LINC00896 prevents miRNA from inhibiting SLC7A11 expression, thereby promoting tumor progression." (PMID 38534739, 2024).
LINC00896 also shares sentences with these, for which no sentence is quoted: autism (1 paper).